MIR8485 (microRNA 8485)
Synonyms: hsa-mir-8485
Gene: MicroRNA gene on chromosome 2 (50,696,172 to 50,696,262, reverse strand). Ensembl gene ENSG00000216191.
Diseases named in the same sentence as MIR8485 in open-access papers:
MIR8485 is named in the same sentence as 1 disease in open-access papers, as found by Europe PMC text mining. Sharing a sentence is not in itself a finding about the gene and the disease. The quoted sentences say what the papers report.
infection (1 paper, 2025). The state of being infected such as from the introduction of a foreign agent such as serum, vaccine, antigenic substance or organism. "Additionally, five genes (CCL26, MIR8485, ULBP1, CCL13, CISH) and one unannotated gene (ENSG00000289505) were downregulated in the transwell relative to the other infection groups." (PMID 40630957, 2025).